VHL (von Hippel-Lindau tumor suppressor)
Diseases named in the same sentence as VHL in open-access papers (continued):
Sharing a sentence is not in itself a finding about the gene and the disease.
tumor (continued). "One patient with a papillary tumor reported a positive family history; no mutations in the VHL gene were observed in the corresponding tumor sample." (PMID 15932632, 2005). "Our results, showing no CA9 accumulation in well-differentiated, non-VHL tumours, are consistent with the fact that VHL mutations have only been reported in the initial progression of a small proportion of PETs." (PMID 15558070, 2005). "The mean tumor size was 72.7 mm for tumors with a VHL mutation compared to 65.3 mm for tumors without a VHL mutation." (PMID 15932632, 2005). "Whether this, or other putative VHL pathways, accounts for the tumor suppressor action is the subject of active investigation." (PMID 15361934, 2004). "Despite more than a decade of intensive investigation following identification of the defective gene in 1993, the nature of the VHL tumor suppressor mechanism and how it relates to the physiological function of VHL remains unclear." (PMID 15361934, 2004). "VHL regulates transcription elongation and is known to act as a tumour suppressor protein." (PMID 14612903, 2003). "However, the precise mechanisms of vHL-related tumor development remain incompletely understood." (PMID 41870981, 2026). "Initial changes likely involve mutated VHL, but as the tumor progresses, VHL status may no longer serve as a key trigger for tumor growth and metastasis." (PMID 40332447, 2025). "Adding to this complexity, mutations in the VHL gene and the activation of the HIF-1α pathway play a crucial role in the development and progression of sporadic HBs, leading to the overexpression of pro-angiogenic factors like VEGF, which further exacerbates HBs tumor angiogenesis and growth." (PMID 40171270, 2025). "The lack of fully reprogrammed cells from ccRRCC VHL+-restored patient tumor cells could be related to the other gene mutations that are also present in ccRCC lines." (PMID 41301058, 2025). "Moreover, in resected RCC tumor tissue high levels of IL-8 production (conveying a higher risk of death) did not appear to correlate with VHL mutational status." (PMID 40839124, 2025). "No FSHR1-positive tumor cells were visible in sections representing VHL-associated ccRCC." (PMID 41024941, 2025). "Under normoxia, HIF-1α is hydroxylated by prolyl hydroxylases and degraded via the Von Hippel–Lindau (VHL) protein, but under hypoxia, it stabilizes to promote the Warburg effect by enhancing glycolysis and reducing oxidative phosphorylation, supporting tumour growth and survival." (PMID 41007296, 2025). "Given that pathogenic germline VHL alterations, particularly deletions, are expected to be highly penetrant, and these patients did not have a syndromic tumor profile (i.e., had only one isolated component tumor), it is likely that these VHL alterations were somatic events." (PMID 40647474, 2025). "Moreover, mechanism-based therapies are being introduced in genetically defined subgroups, as illustrated by the activity of the HIF-2α inhibitor belzutifan in VHL-associated neoplasms, including non-metastatic pNENs." (PMID 41294693, 2025). "Furthermore, high RUNX3 methylation levels presented an ill-defined tumor margin and left-sided tumors, two characteristics, respectively, not present in VHL gene mutation." (PMID 38666933, 2024). "Besides, expression of Flag-VHL in the VHL-deficient ccRCC cells suppressed amino acid starvation-induced autophagy in the tumor cells expressing WT Beclin1, but not Beclin1 P54A (Fig. EV4J)." (PMID 38360997, 2024). "Therefore, the use of blood telomere length as a biomarker for VHL disease may have limitations in accurately predicting tumor risks and disease progression in all individuals with VHL." (PMID 39272694, 2024).
tumor (continued). "To identify HIF2α-independent tumor-suppressing function of VHL and determine whether autophagy is differentially regulated between ccRCC cells and normal kidney cells, we performed immunohistochemistry (IHC) staining of 30 ccRCC specimens with their adjacent normal tissues." (PMID 38360997, 2024). "However, VHL mutation, SETD2 mutation and BAP1 mutation had mutational differences of up to 10% between the two groups, suggesting that differential expression of BID mediates differential tumor mutational signatures." (PMID 38767695, 2024). "However, whether tumor cells differentially respond to these stresses and whether VHL exerts its tumor suppressor activity through direct regulation of autophagy remain unclear." (PMID 38360997, 2024). "Inactivation of VHL leads to aberrant activation of HIF, which in turn causes overexpression of downstream target genes such as VEGF, thereby promoting tumor angiogenesis and tumor cell proliferation, and accelerating tumor progression through multiple mechanisms such as EMT and inflammation." (PMID 39092291, 2024). "Another explanation of why the loss of VHL function and subsequent HIF activation lead to tumorigenesis suggests that the ‘second hit’ would cause loss of pivotal VHL function during organ development, leading to maldeveloped structures that represent prerequisites for tumor formation." (PMID 39272694, 2024). "Since the VHL ko cells do show increased expression of some cytotoxic effector markers relative to WT T cells, this coupled to an initially increased T cell number may account for the differences in anti-tumour responses noted between these studies." (PMID 38690263, 2024). "Hence it is unclear why VHL-positive ccRCC tumours might have a more favourable outcome than VHL-wildtype ccRCC." (PMID 38106039, 2023). "Collectively, our study demonstrates the novel mechanism of PIN1/CDK1 to cooperatively destabilize pVHL and promote tumor progression, thereby targeting PIN1 and CDK1 might be potential therapeutic strategies in the treatment of TNBC and other cancers with wild-type VHL." (PMID 36813923, 2023). "Therefore, these SNPs in VHL may be useful as genetic tumor markers for the molecular diagnostics for ccRCC patients." (PMID 36835190, 2023). "Therefore, these SNPs in VHL may be useful as genetic tumor markers for the molecular diagnostics and for facilitating the development of new treatments for ccRCC patients." (PMID 36835190, 2023). "In addition, SOCS and VHL proteins function as tumor suppressors; consequently, it has been suggested that the inactivation of these proteins may lead to the development of nervous system malignancies." (PMID 36835292, 2023). "As VHL-dependent regulation of miRNAs is well known in RCC, it is important to find the means to overcome such a mutation-related deleterious imbalance by taking advantage of the potential regulation by activation of other tumor suppressors able to control the tumor growth." (PMID 35625614, 2022). "However, due to novel genera under the family of Colwelliaceae, this study intended to characterize the protein EMK97_00595 (Litorilituus sediminis), a family of von Hippel-Lindau (VHL) that have an overwhelming function as a tumor suppressor in higher organisms." (PMID 35399005, 2022). "In addition, comparison of specimens with or without VHL mutations has highlighted differences in the tumor immune signatures that can also associate with response to therapy." (PMID 35663987, 2022). "In our study, neither PBRM1 nor VHL was significantly associated with lower grade tumours." (PMID 35444164, 2022). "In addition, we discovered that OTUD6B mRNA level was in a significant decreasing trend with the development of ccRCC pathological stage (including I–II, III–IV stage or M0, M1 stage) in tumor tissue with or without VHL mutation." (PMID 35110537, 2022).
tumor (continued). "Furthermore, the mutation of VHL alone does not appear to be sufficient to initiate tumor formation, as patients with loss of both copies of VHL can show benign lesions including cysts." (PMID 36077607, 2022). "These are Patient 8 diagnosed at age 13 years with non-metastatic secreting-PGL tumor of lumbosacral location in whom the recurrent CNV in SDHB was identified, and Patient 10 diagnosed at age 9 years with non-metastatic secreting-PCC tumor, who carries the pathogenic variant in the VHL gene." (PMID 36685941, 2022). "Additionally, recently published phase II data examining the PARP inhibitor talazoparib and avelumab in VHL deficient clear cell RCC showed no objective tumor responses." (PMID 36291789, 2022). "Furthermore, a proteomic study aiming at characterizing new partners of the von Hippel Lindau (VHL) tumor suppressor, an essential component of the ubiquitin E3-ligase complex that mediates proteasomal-mediated degradation of HIFs, identified ARF as a partner of the long isoform of VHL." (PMID 33406607, 2021). "For example, cell-intrinsic immunopathology was only observed in VHL-deficient CD8+ T cells in response to persistent antigen resulting from chronic infection, but not in response to acute infections or antigens associated with tumours, where constitutive HIF expression was beneficial." (PMID 34603285, 2021). "Finally, a combination of an AURKA inhibitor, MLN8237 (alisertib) with NVP-BEZ235 in a 786-0 VHL-null mouse xenograft model of RCC dramatically reduced tumor burden, highlighting the potential for co-inhibition of AKT, mTOR and AURKA as a clinical intervention strategy." (PMID 34002003, 2021). "The tumor suppressor von Hippel-Lindau (VHL) gene is one of the most important suppressors of the HIF2α/VEGF pathway and 45% of metastatic RCC present the mutant or lost VHL gene, which might lead to constitutively activated HIF-VEGF signals to induce the RCC progression." (PMID 34572815, 2021). "MiR-21 has also been linked to human tumor invasion and metastasis by negatively regulating targets that are adversely associated with metastatic capacity, such as PTEN, PDCD4, von Hippel-Lindau (VHL), TIMP3, Tropomyosin 1 (TPM1), and Serpin Family B Member 1 (SEPINB1)." (PMID 34066762, 2021). "Therefore, VHL patients need a repeatable nephron-sparing technique to achieve tumor control." (PMID 34414496, 2021). "Importantly, eliminating HIF-2α is sufficient to suppress VHL-defective tumor growth." (PMID 34931765, 2021). "Longer term, the identification of tumour biomarkers that might distinguish between VHL-related and VHL disease-independent haemangioblastomas could enable better stratification of sporadic haemangioblastoma patients and a more personalized approach to continuing surveillance." (PMID 34573396, 2021). "Therefore, the lack of therapies for diffuse or recurrent symptoms leads to an urgent demand of effective drugs for VHL patients, especially those that might halt the tumor progression and, subsequently, delay surgical interventions." (PMID 32854260, 2020). "Moreover, the principal rational is that High CAIX expression could witness the VHL-associated tumorigenesis, and ccRCC presenting an abnormally low CAIX rate could reflect the tumor de-differentiation and aggressiveness." (PMID 32998233, 2020). "Similarly, the VHL E3 ligase is essential for the ubiquitination and degradation of hypoxia-inducible factor-1 alpha (HIF1a), a TF that regulates many genes necessary for tumor growth." (PMID 32718354, 2020). "However, because HIF-1α and HIF-2α have opposing activity in ccRCC with HIF-2α playing the dominant tumor-promoting role, it remains unclear if the VHL-HIF axis is sufficient to explain the downregulated mitochondrial function in ccRCC." (PMID 32929120, 2020). "Furthermore, differential clinical responses to treatment with tyrosine kinase inhibitors and immune checkpoint inhibitors suggest that VHL-independent mechanisms may influence tumor progression in ccRCC." (PMID 33177244, 2020).
tumor (continued). "However, even if VHL biallelic inactivation is a critical founder event, it is not sufficient for tumor development and additional mutations and epigenetic changes are necessary." (PMID 31861590, 2019). "The tumor suppressor VHL encodes a ubiquitin ligase enzyme that presides to constant HIF1α degradation in the presence of molecular oxygen, when the transcription factor is hydroxylated by prolylhydroxylase domain-containing (PHD) enzymes for VHL recognition and proteasome degradation." (PMID 30728892, 2019). "In addition, MYBBP1A could be involved in the plasticity of bioenergetics in cancer cells, as MYBBP1A has been proposed to be regulated by the von Hippel-Lindau (VHL) tumor suppressor." (PMID 30781655, 2019). "However, the relationship of autophagy and VHL in tumor progression remains controversial." (PMID 30902965, 2019). "Within D3 lesions (n = 20), a significant relationship was found between LBD and lower VHL (univariate regression analysis, p = 0.033), indicating that tumour size may have an initial role in VHL expression, but is overshadowed by the effect of M3 as soon as this event occurs." (PMID 31323773, 2019). "Yet, those 23 CRC derived from the four patients without VHL mutation in their tumor tissue could not help the diagnosis of CRC using genetic data." (PMID 29732003, 2018). "Although VHL may be regulated by multiple biomarkers expressed in tumor cells and their adjacent microenvironment, miRNA-155 and -210 emerged as key modulators of VHL function, and may offer an alternative mechanism for stable expression of HIFs in ccRCC tumors." (PMID 30380599, 2018). "Of particular importance to rule out are other VHL-associated neoplasms such as metastatic ccRCC." (PMID 30340515, 2018). "The fact that AC5 was detectable in this tumor without VHL mutation suggests that other mechanisms may contribute to its origin as well." (PMID 29748622, 2018). "However, the loss of VHL alone is not sufficient for tumor initiation and survival, and a fraction of ccRCCs contain wild-type VHL genes, suggesting additional genetic alterations are required in the course of tumor development." (PMID 29158875, 2017). "Our model identified mutations in VHL (von Hippel-Lindau), PBMR1, BAP1, MTOR, ATM, SETD2, KDM5C and PTEN (phosphatase and tensin homolog), as well as copy number changes in MLH1, DUSP1 and RANDBP17 as significantly associated with various TF activity changes across tumours." (PMID 28139702, 2017). "Finally, we attempted to assess whether VHL loss, CDKN2A loss and MYC activation are dysregulated at tumour initiation or tumour progression, by analysing their relative frequency by TNM stage in the TCGA KIRC data set." (PMID 28593993, 2017). "Interestingly, a deleterious frameshift deletion in VHL was present in tumor BC_1L, but no VHL mutation was detected in tumor BC_1R or in the normal peritumoral tissue (BC_1P)." (PMID 27383411, 2016). "Interestingly, although no VHL mutation was detected in tumor BC_1R and BC_2L, mutations in UBE2Q2 and PARK2, two genes involved in ubiquitin-mediated proteolysis, were present in these two tumors, respectively." (PMID 27383411, 2016). "The loss of function of VHL prevents the degradation of HIFá proteins resulting in the increased expression of angiogenic factors including vascular endothelial growth factor (VEGF) and platelet-derived growth factor B chain (PDGF-B) that contribute to growth and expansion of tumor." (PMID 28326269, 2015). "Thus, in VHL mutated patients, it can be speculated that COL6A1 upregulation indicates concurrence with inactivation of other tumor suppressors and may represent a signal of poor prognosis." (PMID 26317545, 2015).
tumor (continued). "In addition, we show here that PNMT gene encoding for the enzyme catalysing the conversion of noradrenaline to adrenaline is hypermethylated and downregulated in VHL tumours, suggesting that epigenetic silencing of this gene explains the noradrenergic phenotype of both VHL- and SDHx-mutated tumours." (PMID 25625332, 2015). "Subsequent to VHL mutation and loss of 3p, no single copy number or mutational event was common to all four tumors, suggesting contingency and the unpredictable nature of tumor evolution subsequent to a similar germline event." (PMID 25159823, 2014). "They found that tumor samples that expressed increased amount of miR92a showed decreased levels of VHL mRNA, suggesting the possibilities that miR92a or some other microRNAs may regulate VHL gene expression in PTC." (PMID 25490036, 2014). "Although further studies with larger sample sizes are needed to address the details of the association of VHL SNPs with RCC, as well as ethnic variation, these SNPs may be useful genetic tumor markers for the molecular diagnostics of clear cell RCC in the elderly population in Taiwan." (PMID 25217002, 2014). "Thus we investigated if FLCN may exercise its tumor suppressing activity downstream from VHL by regulating LC3C or LC3B autophagy." (PMID 23922894, 2013). "However, c-Myc expression was detected in both cell lines, suggesting that PIM kinase inhibition may be an effective therapeutic strategy in both VHL−/− and VHL+/+ tumours." (PMID 22015557, 2011). "Moreover, common germline VHL SNPs and haplotypes were associated with promoter hypermethylation in RCC tumor tissue and may demonstrate an example of facilitated epigenetic variation with respect to inherited high risk genotypes." (PMID 22022277, 2011). "We also found a strong inverse correlation between miR-210 levels and mRNA expression of a miR-210 target gene, ISCU1/2, which may contribute to the repression of mitochondrial proteins by VHL and to the anaerobic pattern of respiration seen in renal (and other) tumours." (PMID 20964835, 2010). "However, we did not observe an association with a history of any of these VHL-related tumours among first-degree relatives." (PMID 20442711, 2010). "VHL also has a number of other important functions that may have tumour suppressor effects." (PMID 20964835, 2010). "Thus, it is highly possible that hypoxia may also inactivate VHL function as a tumor suppressor besides stabilizing HIFα by blocking hydroxylation." (PMID 20300531, 2010). "VHL mutations may be present in a subgroup of patients with negative CAIX expression in tumour tissue but with a high plasma level of CAIX." (PMID 20461082, 2010). "Several other studies, however, were not able to correlate VHL status to clinicopathological parameters or prognosis, and others linked VHL alteration with more advanced tumour stages." (PMID 19755989, 2009). "In addition, we transfected VHL siRNA to normoxic tumor cells to increase the HIF-1α protein level." (PMID 19893619, 2009). "For example, although VHL is primarily inactivated by somatic mutations (promoter methylation occurs in ~15% of sporadic cRCC), inactivation of the RASSF1A TSG in RCC (and in other tumour types) most commonly results from promoter methylation, whilst intragenic mutations are rare." (PMID 19493342, 2009). "In contrast to clear cell RCC, VHL mutations and/or increased expression of hypoxia-inducible genes are not found in these tumor subtypes and molecular genetic defects that are associated with tumor development remain unclear." (PMID 18773095, 2008). "Interestingly, a type 2A VHL mutant (low risk of RCC) was seen to support ciliogenesis, suggesting that with type 2A VHL mutations, renal cells remain differentiated and are therefore not capable of initiating a tumor." (PMID 17598890, 2007). "Indeed, inhibition of HIF-2α is required for tumor suppression by VHL in RCC in vivo." (PMID 17140440, 2006).